CD4 (CD4 molecule)
Diseases named in the same sentence as CD4 in open-access papers (continued):
Sharing a sentence is not in itself a finding about the gene and the disease.
parasitemia (continued). "The up-regulation of HLA-DR,DP,DQ as specifically observed in response of monocytes from chronic toxoplasmosis patients to parasite infection in vitro additionally argues for increased capacities to present antigens to CD4+ T lymphocytes." (PMID 31316920, 2019). "To further investigate the requirements for sustained cellular immunity to an intracellular parasitic infection, we assayed the contribution of CD4+ and CD8+ T cells to the production of IFN-γ, TNF-α and IL-10 in spleen cells of post-challenged animals." (PMID 31739549, 2019). "In conclusion, this study reveals a high prevalence of opportunistic parasitic infections, significantly correlated with diarrhea and low CD4+ T cell count among PLWHA in Nigeria." (PMID 30344850, 2018). "This would speak in favor of a protective role for CD4+gamma-delta+ T cells in helping to control parasitemia." (PMID 30662439, 2018). "Strikingly, caspase-1/11−/− mice showed the most dramatic reduction in the number of IFN-γ- and IL-17-producing CD4+ and CD8+ T cells associated with higher parasitemia and lower survival." (PMID 29774028, 2018). "The importance of CD4+ T cell presence for NK cell-mediated mechanisms has been demonstrated for other parasitic infections." (PMID 30090103, 2018). "IL-10 production can be significantly elevated in the pulmonary mucosa during the late stages of parasitic infection by Nippostrongylus brasiliensis (Nb), predominantly by CD4+ T cells that are LAG3/CD49b double positive." (PMID 30510554, 2018). "TCR-βhiNK1.1+ CD4+ T cells expanded rapidly and remained elevated until peak parasitemia (day 14 p.i.)but contracted significantly upon resolution of the infection at day 24 p.i.." (PMID 30374346, 2018). "infection, which implies that PDL2, but not PDL1, expression on human blood dendritic cells (DCs) is correlated with reduced parasitemia due to enhanced protective CD4+ T cell responses." (PMID 30693001, 2018). "The proportion of PD-1+ and CTLA-4+CD4+ T cells weakly correlated with parasitemia at time of diagnosis." (PMID 29555909, 2018). "In summary, we showed BACH2 is an important intrinsic factor in CD4+ T cells during differentiation in vitro and during parasitic infection." (PMID 30459773, 2018). "Surprisingly, we identified a unique CD4 T cell subset in the skin that was induced by both allergen priming in the skin and parasite infection in the lung that was committed solely to IL-13 expression and was completely independent of IL-4." (PMID 29910811, 2018). "This was consistent with the parasite infection via induction of IL-5 production, accelerating induction of antigen-specific CD4+CD25+ T cells." (PMID 29163523, 2017). "Across viral, bacterial, and parasitic infections, the increased production of IL-10 has been shown to aid in the maturation of memory CD4+ and CD8+ T cells." (PMID 28270815, 2017). "We observed that at the peak of parasitemia, muMT-infected mice presented higher frequency of IFNγ-producing CD4+ T cells than their counterparts in infected WT, but this population rapidly decreased (data not shown)." (PMID 29209313, 2017). "We also showed IL-5 treatment, as with parasitic infection, increased the number of CD4+CD25+ Treg that expressed Il5ra." (PMID 29163523, 2017). "These IL-10 secreting Th1 CD4+ T cells have been identified in parasite infection models, with both effector and regulatory functions." (PMID 28810829, 2017). "Our results are consistent with the roles of CD4+ T cells in mediating the immune response and in eliminating viral, bacterial, fungal, and parasitic infections and malignant cells." (PMID 29267496, 2017). "By contrast, mice without depletion of CD4+ T cells (high plasma levels of IFN-γ) or mice depleted completely of CD4+ T cells (undetectable plasma level of IFN-γ) were unable to control the first wave of parasitemia and died on day 7–10 postinfection." (PMID 28936213, 2017).
parasitemia (continued). "Accordingly, while the CD4+ T cells from 103 parasite infection (LdWTLLO) continued to produce IFN-γ 21 days postinfection, very low levels of IL10 were observed in this group." (PMID 29312315, 2017). "Significantly lower first and second parasitemia peaks were observed in Cd4-/- mice transferred with B6 CD4 T cells at day 20 p.i. compared with those transferred with P2rx7-/- CD4 T cells at day 20 p.i.." (PMID 28859168, 2017). "The Th17 cell is a new type of CD4+ T helper cells, known to protect the body against fungi and parasitic infections and involved in autoimmune and the body's inflammatory response." (PMID 29156727, 2017). "CD4+ helper T (Th) cells play critical roles in both host humoral immunity and cellular immunity against parasitic infection and immunopathology in schistosomiasis." (PMID 29192177, 2017). "Our results significantly increase our understanding of the dynamics and maintenance of IL-10 production by CD4+ T cells postinfection and reveal the functions of IL-10 during secondary parasite infections." (PMID 27630165, 2016). "Using both chronic viral and parasitic infection models, we uncovered a molecular circuit in which type I IFNs directly induce Blimp-1 expression in pathogen-specific CD4 T cells and promote T regulatory 1 responses." (PMID 27732671, 2016). "Pathogen-specific effector CD4 T cells are the major source of IL-10 following prolonged viral and parasitic infection." (PMID 27732671, 2016). "Most significantly, while antibodies and CD4+ T cells can contribute to overall control of parasitemia during re-infection, CD8+ T cells are essential for control at sub-patent levels." (PMID 27217330, 2016). "This study showed that chance of parasitic infections in persons with CD4 T-cell count <200 was 2.5 times higher than those with CD4 T-cell count ≥200." (PMID 27048153, 2016). "In participants categorized by a CD4 T cell count, the rate of parasitic infection was higher in patients with chronic diarrhea." (PMID 27165271, 2016). "The present study confirmed that co-infected patients with active VL (NR or R group) have low CD4+ T cell counts, high levels of cellular activation and microbial translocation and elevated parasitemia." (PMID 27907136, 2016). "69.5 % of parasites identified were opportunistic in nature among which the majority of the opportunistic parasitic infections were observed in the patients with CD4 T-cell count <200." (PMID 27048153, 2016). "A higher rate of parasitic infection was observed among patients that had chronic diarrhea, although the difference was found to be statistically significant only in the CD4 T cell count category 200–499 cells/μl." (PMID 27165271, 2016). "Strikingly, IFNAR signaling blockade decreased Blimp-1 expression in both parasite infection induced- and virus-specific CD4 T cells." (PMID 27732671, 2016). "The chances of parasitic infections in persons with CD4 T-cell count <200 was 2.5 times higher than those with CD4 T-cell count ≥200." (PMID 27048153, 2016). "In studies done in Nepal, more than three-fifth to four-fifth of the HIV patients with CD4 T-cell count <200 had parasitic infections." (PMID 27048153, 2016). "After stimulation, we observed a marked decrease in the number of IFN-γ-producing CD4 T cells responding to flagellin, SseI, and SseJ at day 14 but these responses had largely recovered after the resolution of parasite infection (day 28)." (PMID 26366739, 2015). "Peak parasitemias in the CD4-depleted vaccinated animals reached nearly 60% (compared to 5% in the non-treated immunized mice) and the time to parasite clearance was extended by more than 3 weeks for the CD4–depleted mice relative to the vaccinated controls." (PMID 26505634, 2015). "We also showed that splenic DCs were crucial for the CD4+ T cell response to infection, but full DC maturation was achieved only after the peak of parasitemia." (PMID 25658925, 2015).
parasitemia (continued). "CD4+ T cells play critical roles in both host immune responses against parasitic infection and immunopathology in schistosomiasis,and coordinate many types of immune cells that contribute to fibrosis." (PMID 25590646, 2015). "It is widely acknowledged that the parasitic infection can initiate a successful crosstalk between human immune system and parasite itself and actively modulate CD4+ T cells development, thus guaranteeing its persistent survival." (PMID 26509179, 2015). "Innate immune system is involved in controlling the growth rate and the extent of parasitemia while resolution requires T lymphocytes, specifically the CD4+IFN-γ producers which degrade intraerythrocytic parasite." (PMID 26693364, 2015). "In other parasitic infections such as leishmania and toxoplasma, the functional phenotype of the CD4+ T cell response correlates with the success or failure to clear the pathogen." (PMID 24415936, 2014). "These cells were able to inhibit proliferation of effector CD4+ T cells in vitro and to promote peripheral blood and heart parasitemia in vivo." (PMID 23509755, 2013). "In the absence of CD4 T cells, both naïve and BCG-vaccinated mice fail to control and clear the PyNL infection; extremely high levels of parasitemia (>75%) were seen in CD4-depleted naïve and BCG-vaccinated mice at 26 days post-infection." (PMID 23861742, 2013). "CD4+ T-cells are key in promoting expulsion of intestinal parasite infection, including T. muris, and TGFβ signalling is triggered in these cells early during infection." (PMID 24098124, 2013). "In fact, other reports on apicomplexan parasite infections show that Treg, apart from suppressing CD4+ T cell proliferation and cytokine production, similarly affect CD8+ T cells." (PMID 23937079, 2013). "Persistence of parasitic infestation is due to CD4+CD25+ Treg and these hosts have expanded CD4+CD25+FoxP3+ Treg populations." (PMID 23935597, 2013). "Instead, mice lacking integrin αvβ8 expression on DCs displayed an early increase in production of the protective type 2 cytokine IL-13 by CD4+ T-cells, and inhibition of this increase by crossing mice to IL-4 knockout mice restored parasite infection." (PMID 24098124, 2013). "Eosinophilia induced by parasitic infection is dependent on interleukin-5 produced by Th-2 subset of CD4+ helper T cells." (PMID 23109965, 2012). "Recipients of CD4+CD25+ T cells had higher peak parasitemia and took longer time to control their first wave of parasitemia compared to recipients of CD4+CD25− cells or PBS." (PMID 22860150, 2012). "We showed that adoptive transfer of highly enriched naïve CD4+CD25+ T cells (Tregs) led to increased peak parasitemia and production of disease exacerbating inflammatory cytokines, including IFN-γ, IL-6, TNF and MCP-1 early during infection in C57BL/6 mice." (PMID 22860150, 2012). "On day 10 p.i., in parallel with the control of parasitemia, CD4+ T cell numbers per spleen abruptly decreased to values lower than those of non-infected mice." (PMID 22272258, 2012). "Plasmodium chabaudi infection induces a rapid and intense splenic CD4+ T cell response that contributes to both disease pathogenesis and the control of acute parasitemia." (PMID 22272258, 2012). "T helper 1 (Th1) CD4 cells are usually involved in mycobacterial diseases and sarcoidosis, while T helper 2 (Th2) CD4 cells are usually involved when there is a parasitic infection." (PMID 24278704, 2012). "Consistent with other studies on parasitic infection, we found that CD4+T cells produce higher levels of IFN-γ and IL-10 after CD25+cell depletion following pVAX1-Sj26GST immunization." (PMID 22802961, 2012). "We examined the participation of IL-10 in the inhibition of CD4 T cell effector functions in our co-cultures because this cytokine is secreted by T cells with an effector phenotype in intracellular parasitic infections as well as by Tregs." (PMID 22545172, 2012).
parasitemia (continued). "The infection of C57BL/6 mice with 106 parasitized red blood cells (PRBC) resulted in a rapid increase in splenic CD4+ T cell numbers, attaining maximum levels concomitant with the peak of parasitemia on day 7 post-infection (p.i.)." (PMID 22272258, 2012). "Corroborating with previous studies investigating experimental malaria infection models, the percentages of CD4+CD25+ regulatory T cells increased in the spleen as the parasitemia evolved, with a peak observed on day 4 after infection (6.4%)." (PMID 21464982, 2011). "As seen in this study, an increase in HIV viral load and decreases in the number of CD4+ cells/mm3 and the CD4+/CD8+ ratio were identified as cofactors for increased parasitemia that can be used to target the introduction of early, pre-emptive therapy." (PMID 21912712, 2011). "The strong correlation between the number of parasites and CD4+/CD8+ cells suggests that both cells play a role in the control of parasitemia." (PMID 21912712, 2011). "We suggest that increasing parasitemia in subsequent examinations and/or stabilization at levels higher than previously seen in the same patient should be carefully monitored for CD4+ counts and viral load." (PMID 21912712, 2011). "The highest level of parasitemia was seen in the RE group, which was associated with increased HIV viral load, a decreased number of CD4+ cells, and a decreased CD4+/CD8+ cell ratio; these results confirm the failure of immune mechanisms in the RE group." (PMID 21912712, 2011). "CD4+ T cells play critical roles in both host immune responses against parasitic infection and immunopathology in schistosomiasis." (PMID 22102924, 2011). "Our data suggest that the greater capacity of CD4+ T cells in chronic infection to control early parasitemia is due to the maintenance of Th1 effector cytokine potential by the effector or effector memory cells." (PMID 21124875, 2010). "Our data suggest that chronically stimulated memory CD4+ T cells are the most protective for controlling early parasitemia and pathology, as seen in Leishmania infections, another low-level chronic infection." (PMID 21124875, 2010). "The rate of parasitic infection was increased with decreasing CD4 T-cell count among HIV infected individuals." (PMID 19765310, 2009). "Of the CD4+ T cell subtypes examined, activated CCR5+ memory CD4+ T cells strongly proliferated in response to parasitemia as well as central memory CD4+ T cells which are generated to respond to subsequent infections." (PMID 19774084, 2009). "In five of them, PCR was negative and CD4 cells count was higher than the first determination, or almost the same; the last patient had an increased parasitemia level accompanied by a reduced CD4 cells count." (PMID 20003257, 2009). "Especially important in this regard are responses of CD4+αβ T cells, because of their predominant role in bacterial and parasitic infections in pigs." (PMID 19196461, 2009). "As we have demonstrated here, there is an increase in the numbers of HIV-receptive CCR5+ CD4+ T cells in response to parasitemia." (PMID 19774084, 2009). "CD4+/CD8+ T cell ratios fluctuated with the initial parasitemias but stabilized following the third." (PMID 19774084, 2009). "Simultaneously, CD4 counts were recorded to assess the status of HIV infection vis-à-vis parasitic infection." (PMID 18713475, 2008). "Lower levels of IL-12 in fatal kala-azar may be justified by its role as a cytokine that activates CD4+ type 1 helper T cells, stimulating natural killer (NK) cells to produce IFN-γ, in addition to being associated with lower parasitemia in kala-azar." (PMID 41003560, 2025). "We discuss how adjuvants engaging this pathway might enhance protective TH2 immunity to parasitic infections while drugs that block the activity of Chi3l1 in DCs and CD4 T cells might prevent damaging TH2 responses in the settings of allergic inflammation." (PMID 41012147, 2025).
parasitemia (continued). "The coordinated activation of CD4+ and CD8+ T lymphocytes constitutes a critical defense mechanism against T. gondii infection, with CD8+ T cells playing a particularly vital role in controlling acute parasitemia through synergistic interactions with CD4+ T cells." (PMID 41321568, 2025). "We confirmed prior data demonstrating that CD4+ T cells are required for clearance of the parasite during infection, as absence of these cells in CD4-/- mice resulted in the development of long-term persistent parasitemia." (PMID 39452729, 2024). "The current study, in combination with our previous study of primary B. microti infection, indicates that CD4 T cells, and to a lesser extent B cells, contribute to resolution of primary infection as determined by clearance of parasitemia and protection against secondary challenge." (PMID 38392861, 2024). "In addition, a colony of IFN-γ-producing Leishmania-specific memory CD4+ Trm cells that formed in response to parasitic infection were able to remain in the skin when transplanted into juvenile mice." (PMID 38779662, 2024). "Likely, the simultaneously reduced nTreg and IFN-γ (or IL-17A)-secreting CD4+ T cells may considerably explain the comparable parasitemia in WT versus RACK1 KO mice during the early phase of infection." (PMID 39024388, 2024). "The main factors associated with all-cause mortality were higher parasitemia, lower CD4 counts/μL, higher viral load, and absence of antiretroviral therapy." (PMID 38408095, 2024). "Chronic parasitic infection may inhibit the immune system’s defenses against HIV-1, while concomitant immunological activation may cause HIV-1-infected individuals to lose CD4 cells more quickly." (PMID 39057072, 2024). "The proportions of CD4+ T cells in peripheral blood (PB) were significantly higher at day 7 and 28 compared to wild‐type (WT) for Ebi3−/− mice and at day 21 for Il‐27−/− mice, although parasitemia levels were comparable." (PMID 37855243, 2023). "Two patients, with a CD4 cells count equal to 350 cells/μL and with quantitative xeno without evidence of high parasitemia under the risk of reactivation, were treated with benznidazole for 60 days, presenting negative post-treatment xeno." (PMID 36287507, 2022). "However, T cell-specific Ac ablation had no impact on the course of P. yoelii infection as Ac CD4cre KO (Asah1/Cd4cre/+) and Ac CD4cre WT (Asah1/Cd4+/+) mice showed similar spleen weights and parasitemia 7 and 14 days p.i.." (PMID 36094170, 2022). "In contrast, mice could clear the parasites after CD4+ T cells were depleted during the recurrence stage, although the depletion of CD4+ T cells also significantly elevated the P. chabaudi parasitemia." (PMID 35250958, 2022). "The associated factors to the acquisition of parasitic infections were CD4 cell counts below 100 cells per microliter of blood, not washing hands, not being dewormed in the previous 1 year and using water from contaminated open sources particularly, the wells." (PMID 36762162, 2022). "Interestingly, a recent paper showed that IL-18-MyD88 signaling is critical in expanding CD4+IFNγ+ T cells during parasitic infection." (PMID 34093543, 2021). "Thus, it makes sense that co-infected PWH, particularly those with low CD4 counts, have higher parasitemia levels than their HIV-negative counterparts, even in the absence of symptomatic reactivation disease." (PMID 34842854, 2021). "In addition, the role of CD4+ cells (Th1 response) in protecting against increased T. cruzi parasitemia has been demonstrated by higher parasitemia in CD4+ depleted mice." (PMID 34591866, 2021). "After depletion, only vaccinated mice that received CD8+ T-cell-depleting antibodies or rat Ig survived challenge, while mice injected with CD4+ T-cell-depleting antibodies demonstrated a complete inability to control parasitemia, and all succumbed to infection." (PMID 34663097, 2021).